DICER1 (dicer 1, ribonuclease III)
Diseases named in the same sentence as DICER1 in open-access papers (continued):
Sharing a sentence is not in itself a finding about the gene and the disease.
DICER1 syndrome (72 papers, 2015 to 2026). "Thyroblastoma, however, is unrelated to the hereditary DICER1 syndrome, but is associated with somatic mutations in DICER1." (PMID 40892116, 2025). "DICER1 syndrome, which stands for DICER1-related pleuropulmonary blastoma cancer predisposition syndrome, is passed down through families in a reduced-penetrance autosomal dominant fashion." (PMID 39857323, 2025). "SLCTs and renal tumors have recently been linked to DICER1 syndrome, an inherited cancer predisposition syndrome also known as DICER1-related pleuropulmonary blastoma cancer predisposition syndrome (OMIM 601200)." (PMID 40862798, 2025). "Recent studies have reported that the vast majority of patients with ASK have DICER1 variants, and that these tumors are part of the DICER1 syndrome, a hereditary cancer predisposition disorder." (PMID 40861331, 2025). "Given the association of SLCTs with DICER1 syndrome, genetic testing was performed to verify the presence of mutations in the DICER1 gene." (PMID 40862798, 2025). "DICER1 syndrome is associated with a wide range of characteristic tumors and dysplastic disorders caused by heterozygous germline pathogenic variants in the DICER1 gene." (PMID 40892116, 2025). "In individuals diagnosed with DICER1 syndrome, the majority of tumors develop in those who inherit a DICER1 mutation and also acquire an additional somatic missense mutation in the 5′ “hot-spot” codons of the RNAse IIIb domain." (PMID 39860595, 2025). "Genetic testing revealed a pathogenic mutation in the DICER1 gene c.2531_2532del, confirming the diagnosis of DICER1 syndrome." (PMID 39963649, 2025). "In ERMS with DICER1 mutations, genetic counseling is necessary to investigate the possibility of DICER1 syndrome." (PMID 40161378, 2025). "DICER1 syndrome, caused by heterozygous germline mutations in the DICER1 gene, confers a lifetime risk of a variety of neoplastic and dysplastic lesions." (PMID 40469416, 2025). "The carcinogenesis associated with DICER1 has primarily been investigated in people with pathogenic germline gene mutations, resulting in the total loss of one allele of DICER1 (refer to the section on DICER1 syndrome)." (PMID 39857323, 2025). "The diagnosis of DICER1 syndrome is established when a heterozygous germline LOF or suspected DICER1 LOF variant is found by sequence analysis." (PMID 40940982, 2025). "DICER1 syndrome (OMIM 601200) is a rare autosomal dominant tumor susceptibility syndrome caused by heterozygous germline pathogenic alterations in the DICER1 gene on chromosome 14q32.1." (PMID 40226310, 2025). "Based on the diagnosis of ASK and the family history of DICER1-associated tumors, DICER1 syndrome was suspected." (PMID 40861331, 2025). "In patients with DICER1 syndrome, characterized by germline DICER1 mutation, somatic DICER1 mutations in thyroid nodules represent a second hit." (PMID 41175860, 2025). "DICER1 syndrome is an autosomal dominant hereditary cancer predisposition disorder caused by germline pathogenic variants of DICER1." (PMID 40861331, 2025). "DICER1 syndrome (OMIM 601200) is a rare autosomal dominant familial tumor susceptibility disorder with heterozygous DICER1 germline mutations." (PMID 40226310, 2025). "Data from the DICER1 syndrome registries showed that 15% of primary ovarian tumors in individuals with a germline pathogenic variant in DICER1 were diagnosed prior to 8 years of age." (PMID 40940982, 2025). "In fact, genetic mutations (somatic and germline) have been detected in DICER1 and are genetically associated with at least two clinical syndromes: DICER1 syndrome and GLOW syndrome." (PMID 39857323, 2025). "In contrast, new research shows that DICER1 syndrome individuals had a somatic mutation in the second DICER1 gene allele in addition to inherited alterations in the first allele." (PMID 39857323, 2025). "DICER1 syndrome, which mainly affects children and young adults, is usually caused by a germline loss-of-function DICER1 mutation." (PMID 40361440, 2025).
DICER1 syndrome (continued). "A better understanding of DICER1 variants as the cause of DICER1 syndrome and DICER1 syndrome-related endocrine manifestations has also prompted the study of DICER1-driven thyroid disease in both pediatric and adult thyroid nodules." (PMID 38254836, 2024). "While it is crucial to identify individuals with DICER1 syndrome for surveillance purposes, it’s essential to note that most individuals with DICER1 syndrome are either healthy or experience only minor DICER1-associated conditions." (PMID 38254836, 2024). "Characterized for the first time in 2009, the DICER1 syndrome is a multi-tumor condition caused by germline pathogenetic variants in the DICER1 gene and associated with different neoplastic lesions affecting the lungs, thyroid gland, ovaries, and kidney." (PMID 38637342, 2024). "Specific attention was given to thyroid follicular nodular disease and differentiated thyroid carcinomas in infancy as highly indicative of germline DICER1 mutation or DICER1 syndrome." (PMID 38254836, 2024). "In patients with DICER1 syndrome, germline DICER1 mutations are the most prevalent, although somatic DICER1 mutations can also occur presenting as multiple and bilateral thyroid nodules." (PMID 38254836, 2024). "In 2022, the World Health Organization (WHO) described the DICER1 syndrome as an “autosomal dominant tumor predisposition syndrome caused by heterozygous germline pathogenic variants in DICER1”." (PMID 38254836, 2024). "Thyroid follicular nodular disease and differentiated thyroid carcinomas in infancy are highly specific manifestations of germline DICER1 mutation or DICER1 syndrome." (PMID 38254836, 2024). "In the lesions of DICER1 syndrome patients, the co-occurrence of a germline DICER1 variant, often loss-of-function, with a second missense somatic mutation was observed, and tumorigenesis induced by double-hit mutations has been proposed." (PMID 37867524, 2023). "In this report, we present two cases of teenage females who appeared to have DICER1 syndrome based on the clinical presentation and the identification of somatic DICER1 hotspot mutations." (PMID 37248399, 2023). "Given the association of TFND and SLCT with DICER1 syndrome, germline and tumour DNA were subjected to DICER1 screening." (PMID 37248399, 2023). "DICER1 syndrome is an autosomal dominant familial tumor predisposition disorder involving a heterozygous DICER1 germline mutation." (PMID 37461056, 2023). "The reclassification of the ovarian tumour, leading to recognition of the association with DICER1 syndrome and the characterization of the germline intronic variants were all applied to recently described DICER1 variant classification rules." (PMID 37248399, 2023). "In human, dysregulation of DICER1 is associated with a wide range of pathologies ranging from DICER1 syndrome, cancer, neurological diseases such as Parkinson’s disease, and autoimmune disorders such as rheumatoid arthritis." (PMID 37158599, 2023). "Somatic mutations in the RNase IIIb domain of DICER1 impair its ability to generate mature 5p miRNAs and are believed to drive tumorigenesis in DICER1 syndrome-associated and sporadic thyroid tumors." (PMID 36896180, 2023). "It should be noted that for some patients multiple specimens were tested and that some pedigrees of DICER1 syndrome carriers are included, thus possibly representing a slight overestimation of DICER1 mutation frequency in TC." (PMID 37867524, 2023). "DICER1 syndrome (OMIM #601200) is a rare tumour predisposition syndrome caused by pathogenic germline variants in DICER1." (PMID 37248399, 2023). "In a previous study, mosaic DICER1 variants were also reported to be associated with DICER1 syndrome in patients with severe phenotypes." (PMID 35163487, 2022). "Here, we describe a rare association of congenital spinal hamartoma and DICER1 syndrome in a 5-week-old infant, with molecular findings suggestive of the implication of DICER1 in the pathogenesis of this tumor." (PMID 36059709, 2022).
DICER1 syndrome (continued). "In a study on macrocephaly associated with the DICER1 syndrome, the number of subjects with a head occipitofrontal circumference above the 97th percentile was significantly higher in patients with DICER1 PVs (28/67, 42%) than in family controls (5/43, 12%)." (PMID 35163487, 2022). "DICER1 syndrome is an autosomal dominant manner caused by a germline DICER1 PV, an important component of the microRNA processing pathway." (PMID 35163487, 2022). "While the majority of DICER1 mutations represent germline variants in the setting of the inherited DICER1 syndrome, sporadic diseases with DICER1 mutations have been recently recognized, albeit rare." (PMID 34282560, 2022). "Mutations of DICER1 are associated with susceptibility to various cancers, which was named DICER1 syndrome." (PMID 35743796, 2022). "DICER1 syndrome is a well-characterized cancer predisposition syndrome caused by a germline mutation in the DICER1 gene, which shows variable expressivity." (PMID 36059709, 2022). "Germline pathogenic variants in DICER1 cause DICER1 syndrome, an autosomal dominant, pleiotropic tumour predisposition syndrome with variable expressivity and reduced penetrance for specific dysplastic and neoplastic lesions." (PMID 33208384, 2022). "Although there is a clear association of this rare ocular neoplasm with PPB and with DICER1 syndrome, only one patient in these reports had germline and a somatic DICER1 testing performed with a paternally inherited germline DICER1 mutation." (PMID 34599283, 2022). "Most known families with pathogenic DICER1 variants have been identified through clinical findings of the hallmark tumours, which can cause ascertainment bias associated with the DICER1 syndrome." (PMID 34552563, 2021). "While most individuals with DICER1 syndrome are heterozygous for a germline LoF DICER1 pathogenic variant, other predisposing DICER1 alterations have also been documented as somatic mosaicism." (PMID 33922805, 2021). "For CN, the occurrence of bilateral tumors is likely largely explained by underlying germline DICER1 mutations, although only 12/167 reported patients with CN were tested for DICER1 syndrome." (PMID 33673661, 2021). "Most frequently, germline loss-of-function mutations in DICER1 combined with a somatic mutation in hotspot (D1705, D1709, G1809, D1810, and E1813) of the RNase IIIb region contribute to the DICER1 syndrome, manifesting as susceptibility to various tumors." (PMID 34322384, 2021). "Early-onset, familial, or male MNG should also alert to the possibility of DICER1 syndrome, especially in the case of a family history of other DICER1-associated cancers." (PMID 33495912, 2021). "It was shown that in cancers associated with DICER1 syndrome as well as other early childhood cancers (e.g. Wilms' tumor), a specific pattern of somatic DICER1 second-hit missense mutations occurs." (PMID 33406242, 2021). "DICER1 syndrome is an autosomal dominant disorder with decreased penetrance, caused by heterozygous inactivating germline DICER1 gene mutations." (PMID 33495912, 2021). "In DICER1 syndrome-associated neoplasms, predisposing loss-of-function mutations in DICER1 typically occur together with a characteristic somatic missense hotspot mutation on the second allele." (PMID 33846547, 2021). "DICER1 syndrome is a rare condition caused by germline variants of DICER1; the occurrence of a second somatic tissue-specific mutation leads to different phenotypes ranging from benign lesions to malignant tumors." (PMID 33552988, 2020). "In pediatric patients with Cushing’s disease, mutations in DICER1, a small RNA processing endoribonuclease that cleaves precursor microRNAs (miRNAs) into mature miRNAs, lead to DICER1 syndrome." (PMID 33266265, 2020).
DICER1 syndrome (continued). "The DICER1 syndrome represents an emerging inherited multineoplastic disorder caused by germline DICER1 gene mutations and characterized by an array of topographically and phenotypically diverse neoplasms of benign, low-grade, or aggressive nature." (PMID 32507920, 2020). "Germline mutations of DICER1 have been well documented in a wide range of tumors in cancer susceptibility syndrome—DICER1 syndrome." (PMID 32629665, 2020). "Mutations in the miRNA enzyme gene DICER1 have been reported in several endocrine malignancies and is associated with the rare tumour-predisposing DICER1 syndrome." (PMID 32163919, 2020). "With ongoing research efforts on DICER1 mutations, genetic screening and counselling on a regular basis is recommended for predicting potential future cancer risk of individuals with DICER1 syndrome family history." (PMID 32629665, 2020). "Context: The DICER1 syndrome is a multiple neoplasia disorder caused by germline mutations in the DICER1 gene." (PMID 32714280, 2020). "DICER1 syndrome is a rare genetic condition predisposing to hereditary cancer and caused by variants in the DICER1 gene." (PMID 33552988, 2020). "Advances in the NGS technology have established a formidable basis for precise and early detection of key genetic alterations (e.g., DICER1 mutations) mediating DICER1 syndrome." (PMID 32629665, 2020). "DICER1 syndrome is a cancer-predisposing disorder caused by pathogenic variants in the DICER1 gene (OMIM 606241), which are known to confer a lifetime risks for a variety of neoplastic and dysplastic lesions." (PMID 33552988, 2020). "Mosaic DICER1 mutations have also been associated with DICER1 syndrome, in addition to the inherited germline mutations." (PMID 29762508, 2018). "A total of 244 articles were collected since the discovery of DICER1 syndrome, and 36 were selected that represented DICER1 pathogenic germline mutations." (PMID 29762508, 2018). "Cases represented in the PubMed database were identified using keywords “DICER1 syndrome”, “DICER1 mutations”, and “Pleuropulmonary Blastoma Familial Tumor Susceptibility Syndrome”." (PMID 29762508, 2018). "Here, we present a review of mutations in the DICER1 gene, the respective protein sequence changes, and clinical manifestations of DICER1 syndrome." (PMID 29762508, 2018). "Pathogenic germline mutations of the DICER1 gene linked to DICER1 syndrome are included in this review." (PMID 29762508, 2018). "DICER1 syndrome is caused by heterozygous germline P/LPV in DICER1." (PMID 40361475, 2025). "DICER1 syndrome, a rare autosomal dominant familial tumor predisposition syndrome, that often manifests in infants and children under 30 years of age, is associated with heterozygous germline DICER1 mutations." (PMID 40007992, 2025). "Similarly, in the context of DICER1 syndrome, germline DICER1 mutations have been found to predispose individuals to a range of tumors, with the tumors retaining one functional DICER1 allele, indicating a haploinsufficiency mechanism." (PMID 40666073, 2025). "Thus, even if the majority of DICER1 mutations in thyroid tumors are somatic, germline testing should be performed to identify patients with DICER1 syndrome." (PMID 41175860, 2025). "Mutations in the DICER1 gene have been linked to various cancers, notably DICER1 syndrome." (PMID 41188596, 2025). "Patients with DICER1 syndrome (a heterozygous germline pathogenic mutation on the DICER1 gene) have an increased risk of developing a variety of tumors, benign and malignant; examples of locations include the lungs, thyroid, kidney, head, neck, and gastrointestinal tract." (PMID 39963649, 2025). "In DICER1-mutated thyroid nodules, benign or malignant, diagnosed with nodular goiter, the prevalence of a coexisting germline mutation indicative of DICER1 syndrome may be as high as 13%." (PMID 41175860, 2025).
DICER1 syndrome (continued). "As mentioned in the previous segment on neoplasia, it has been proposed that the development of tumors in DICER1 syndrome is caused by the inactivation of one allele of the DICER1 gene in the germline, followed by the acquisition of a somatic mutation in the lasting allele." (PMID 39857323, 2025). "The cumulative model in which biallelic mutations in DICER1 with superimposed genetic alterations lead to malignant transformation may explain the reason why DTC is also a common finding in DICER1 syndrome." (PMID 38254836, 2024). "This pathological germline variation in DICER1 may create a predisposition to hereditary cancer syndrome - DICER1 syndrome, characterized by developing multiple benign and malignant tumors." (PMID 36777814, 2023). "Similarly to this work, a few reports have described DICER1 intronic variants (either germline or somatic) in patients with phenotypes associated with DICER1 syndrome." (PMID 37248399, 2023). "Given DICER1 syndrome confers increased risk of certain rare tumours, the detection of one of these distinctive neoplasms or a combination thereof, should prompt genetic DICER1 testing." (PMID 37248399, 2023). "Moreover, in view of the extreme rarity of this neoplasm, the presence of a DICER1 variant in young patients should lead to constitutional testing for DICER1 syndrome." (PMID 38136408, 2023). "DICER1 syndrome is caused by germline pathogenic mutations in the DICER1 gene." (PMID 36151231, 2022). "Interestingly, DICER1 syndrome patients often carry deleterious germline DICER1 mutations, and develop somatic, second-hit type missense mutations in hotspot regions of the RNAse II domain." (PMID 32712880, 2021). "The estimated frequency of loss-of-function DICER1 variants in the general population is suggested to be ~ 1:10,600, which is a substantial higher number compared to the number of identified families with DICER1 syndrome." (PMID 34552563, 2021). "Although no germline DNA was available for study in the current paper, four DICER1-mut ERMS showed a combination of a DICER1 frameshift or nonsense, and a DICER1 hotspot mutation, consistent with alterations previously reported in DICER1 syndrome associated ERMS." (PMID 33846547, 2021). "Studies need to be conducted regarding the morphological features of nodular goitre in individuals harbouring DICER1 variants, and whether they - in case distinguishing hallmarks can be identified - may be suggestive of DICER1 syndrome." (PMID 34552563, 2021). "Most individuals with DICER1 syndrome have a germline loss-of-function DICER1 mutation with a second tumor-specific missense mutation in the RNase IIIb domain; these tumor-specific RNase IIIb missense mutations usually involve one of five hot spot codons (E1705, S1709, G1809, D1810, and E1813)." (PMID 33495912, 2021). "Directions for future research are the natural history and growth rate of DICER1-associated tumors (especially lung cysts and thyroid nodules), the prevalence of adult tumors associated with DICER1 syndrome, and the clinical utility of proposed DICER1 syndrome surveillance protocols." (PMID 34170462, 2021). "DICER1 syndrome encompasses a variety of benign and malignant manifestations including multinodular goitre, which is the most common manifestation among individuals carrying pathogenic DICER1 variants." (PMID 34552563, 2021). "As MNG is one of the most common diseases of the thyroid gland and the most common manifestation associated with the DICER1 syndrome, we have studied the prevalence of pathogenic germline DICER1 variants in a Danish cohort of young individuals operated for MNG." (PMID 34552563, 2021). "Recent reports enumerate anaplastic sarcoma of the kidney in DICER1 syndrome, correlating the germline DICER1 mutations with the development of these tumors, and postulate that they may arise from pre-existing pediatric cystic nephromas." (PMID 33552988, 2020).